EEF1AKMT2 (EEF1A lysine methyltransferase 2)
Description:
[Isoform 2]: Protein-lysine methyltransferase that selectively catalyzes the trimethylation of EEF1A at 'Lys-318'.
Synonyms: C10orf138; METTL10; Efm4
Tractability: PROTAC: ubiquitination databases record sites on it.
Gene: Protein-coding gene on chromosome 10 (124,748,149 to 124,791,887, reverse strand). Ensembl gene ENSG00000203791.
Subcellular location: Cytoplasm; Nucleus
Subcellular location (Human Protein Atlas): Cytosol; Nucleoplasm
Pathways (Reactome):
Metabolism of proteins: Protein methylation
Gene Ontology:
Molecular function: methyltransferase activity; protein-lysine N-methyltransferase activity
Biological process: positive regulation of translational elongation
Cellular component: cytoplasm; cytosol; nucleoplasm; nucleus
Genetic constraint (gnomAD): Loss-of-function variants: 15 observed, 14.44 expected, observed/expected ratio (o/e) 1.04, 90% interval 0.69 to 1.59. The upper end of that interval is the gene's LOEUF score, 1.59, which puts it in group 6 of 6, group 1 being the genes least tolerant of losing a copy. Missense variants: 201 observed, 203.41 expected, observed/expected ratio (o/e) 0.99, 90% interval 0.88 to 1.11. Synonymous variants: 82 observed, 80.11 expected, observed/expected ratio (o/e) 1.02, 90% interval 0.86 to 1.23.
Homologues: Orthologues: chimpanzee EEF1AKMT2 (99% identical), macaque EEF1AKMT2 (70% identical), rabbit EEF1AKMT2 (67% identical), dog EEF1AKMT2 (66% identical), guinea pig EEF1AKMT2 (65% identical), pig EEF1AKMT2 (65% identical), mouse Eef1akmt2 (62% identical), rat Eef1akmt2 (60% identical), tropical clawed frog METTL10 (43% identical), zebrafish eef1akmt2 (42% identical), Drosophila melanogaster CG9643 (32% identical), Caenorhabditis elegans F29B9.1 (26% identical).
Diseases named in the same sentence as EEF1AKMT2 in open-access papers:
EEF1AKMT2 is named in the same sentence as 6 diseases in open-access papers, as found by Europe PMC text mining. Sharing a sentence is not in itself a finding about the gene and the disease. The quoted sentences say what the papers report.
glaucoma (1 paper, 2025). Increased pressure in the eyeball due to obstruction of the outflow of aqueous humor. "The EEF1AKMT2 and MAPKAPK5-AS1 genes were expressed in RGCs, which are the primary cell types that degenerate in glaucoma." (PMID 41328997, 2025).
EEF1AKMT2 also shares sentences with these, for which no sentence is quoted: cancer (2 papers); gastric cancer (1); gastric tumor (1); ovarian tumor (1); tumor (1).